CUL4A (cullin 4A)
Diseases named in the same sentence as CUL4A in open-access papers (continued):
Sharing a sentence is not in itself a finding about the gene and the disease.
cancer (continued). "A growing body of evidence indicates that CUL4A can function as an oncogene in different tumor types, and thus can be used as a prognostic molecular biomarker for different cancers." (PMID 26840256, 2016). "CUL4A overexpression contributes to tumor progression, metastasis, and poorer survival rate of cancer patients." (PMID 26460955, 2015). "The increased Gli1 expression was evident observed only in the cancer cells with enlarged cell nuclei (arrows), located in the identical regions where Cul4A was overexpressed." (PMID 26218750, 2015). "This would be consistent with a specific dependence of the CUL4A function acquired in CUL4A-overexpressing cancer cells." (PMID 24870930, 2014). "On the pathology front, CUL4A is attacked by several viral proteins, and its overexpression is a common feature of many human cancers." (PMID 24522884, 2014). "Overall, the average CUL4A mRNA levels in the cancer tissues were significantly higher than that in the normal lung tissues (P <0.001)." (PMID 25413624, 2014). "The Cul4A gene is located on human chromosome 13q34 and this region is amplified in several cancers, including liver cancer." (PMID 25421893, 2014). "In this review, the authors updated the recent understanding of the two Cullin 4 family members, Cullin 4A and Cullin 4B in human cancer and neuronal disease development." (PMID 23227454, 2012). "CUL4A has been shown to play an oncogenic role in various cancer types." (PMID 34207079, 2021). "Our findings provide evidence for future cancer therapy by interference with CUL4A or CUL4B." (PMID 32587774, 2020). "Cul4a is the core protein of CRLs E3 ubiquitin ligase complex; while it is known that Cul4a is responsible for various cancers, its role in cardiac function remains unclear." (PMID 31178959, 2019). "Ubiquitin E3 ligase CUL4A plays important oncogenic roles in the development of cancers." (PMID 31409387, 2019). "Abnormal expression of Cul4a is closely related to various cancers." (PMID 31178959, 2019). "Cullin 4A (Cul4A) is overexpressed in a number of cancers and has been established as an oncogene." (PMID 31052599, 2019). "Amplification and overexpression of CUL4A have been observed in primary breast cancers and others types of cancers such as hepatocellular carcinomas, so it could be considered as a potential predictive and prognostic indicator of some cancers." (PMID 29707520, 2018). "CUL4A has been known for its oncogenic properties in various human cancers." (PMID 28576144, 2017). "Because of the important role of CUL4A in the ubiquitin-proteasome system, which plays a role in diverse cellular processes, development of drugs targeting the system is a promising and vital field in cancer therapy." (PMID 28576144, 2017). "Accumulating evidence has demonstrated that CUL4A plays a critical role in cancer development." (PMID 28336923, 2017). "Although the oncogenic role of CUL4A has been well established, specific DCAFs involved in cancer development remain largely unknown." (PMID 28336923, 2017). "All evidence indicates that CUL4A is a critical oncogene in cancer development." (PMID 28336923, 2017). "Cullin 4A (Cul4A) has been observed to be overexpressed in various cancers." (PMID 26969027, 2016). "Moreover, knockdown of Cul4A also inhibited anchorage‐dependent and anchorage‐independent colony formation assays of cancer cells." (PMID 26969027, 2016). "Because Cul4A is amplified and overexpressed in cancers and is related to cancer cell survival, growth, proliferation and chemosensitivity, we thus proposed that Cul4A may be a potential target of anticancer therapy." (PMID 26969027, 2016). "Compared to the GES-1 cell line, all cancer cell lines expressed higher levels of CUL4A protein." (PMID 26840256, 2016). "Epithelial-mesenchymal transition (EMT) is a major process in the initiation of cancer cell invasion; therefore, we tested whether the up- or down-regulation of CUL4A resulted in changes to EMT markers." (PMID 26840256, 2016).
cancer (continued). "Increased Cul4A copy number has been reported in several human cancers." (PMID 26218750, 2015). "CUL4A and CUL4B share extensive homology and functional redundancy, however CUL4A has drawn much more attention as a result of a large body of evidence demonstrating its association with cancer." (PMID 26460955, 2015). "Moreover, knockdown of CUL4A/B inhibits the growth of cancer cells, while CUL4A/B overexpression promotes malignant proliferation." (PMID 26460955, 2015). "In addition, it was shown that CUL4A levels can be used as a biomarker for predicting cancer cell sensitivity to a particular therapeutic." (PMID 26684807, 2015). "Consistent with this, knockdown of CUL4A leads to inhibition of cancer cell growth and apoptosis, indicating that CUL4A may be a promising target for anti-cancer therapies." (PMID 25421893, 2014). "More importantly, given their critical roles in tumorigenesis, the authors speculated that Cullin 4A and Cullin 4B could be potentially pursued as new targets for cancer prevention." (PMID 23227454, 2012). "However, the relationship between CUL4A and autophagy in cancer is unclear." (PMID 34257560, 2021). "However, the relationship between CUL4A and autophagy in cancer is still unclear." (PMID 34257560, 2021). "Thus, disruption of the interactions of CUL4A/4B-DDB1 could be an effective strategy to treat cancer with CUL4A/4B-overexpression." (PMID 32140073, 2020). "Overexpression of CUL4A may lead to the proliferation, progression, and metastasis of cancer." (PMID 28576144, 2017). "However, the specific CUL4A-DCAF nexus that contributes to human cancer development remains largely unknown." (PMID 28336923, 2017). "Unsurprisingly, there are increasing number of studies focused on the relationship between CUL4A and tumorigenesis, since deregulation of the cell cycle and genome instability, i.e., two of the most common features of cancer cells, may result from abnormal CUL4A expression." (PMID 28576144, 2017). "Thus, aberrant expression of CUL4A/B contributes to unstable cyclin E level leading to unusual cell cycle, which may induce relevant cancer." (PMID 26460955, 2015). "Genes such as PARP1, NAMPT, AIMP2, MCL1, and TOMM20 exhibited widespread amplifications of CNVs in multiple cancers, while genes like RNF146, GPX4, ESR1, CUL4A, and PTEN showed widespread deletions." (PMID 38499384, 2024). "Another significant gene, DTL, part of the ubiquitin-proteasome system involving CUL4A, shows elevated expression in cancers, and DTL knockdown hinders cancer cell functions." (PMID 39567714, 2024). "Studies in mice using either overexpression or silencing approaches indicate that both CUL4A and CUL4B play a tumor-promoting role in many cancer types including lung, breast, colon, and hepatocellular carcinomas." (PMID 34604860, 2021). "The two cullin paralogs CUL4A and CUL4B, which form the CRL4 ligase scaffold, were depleted in cancer cells by small interfering RNA followed by analysis of the cellular and biochemical responses to ICLs elicited upon cisplatin or MMC treatment." (PMID 31690264, 2019). "However, only a few studies have examined whether CUL4A regulates cancer cell invasion." (PMID 26840256, 2016). "For instance, more studies are apparently needed to further distinguish the functional distinction between CUL4A and CUL4B in cancer." (PMID 26460955, 2015). "For example, PLEC, ANXA10, EHF, SLC4A, and CUL4A are expressed at high levels in MDA-MB-231 relative to MCF-7 cells, and MAGED1, SYK, and EPCAM are expressed at higher levels in triple-negative cancer tissues relative to non-invasive control tissues." (PMID 26053433, 2015).
cancer (continued). "On other hand, silencing CUL4A expression in NSCLC cells reduced proliferation, promoted apoptosis and resulted in tumor growth inhibition in cancer xenograft model." (PMID 25413624, 2014). "Previous studies have suggested the importance of both CUL4A and CUL4B in cancer." (PMID 34604860, 2021). "As mentioned early, CUL4A and CUL4B are overexpressed in many cancer types 14-19." (PMID 32140073, 2020). "Finally, we found that CUL4A downregulated P21 to promote cell cycle progression, and that CUL4B facilitated cancer cell survival by downregulating FOXO3A by accelerating the degradation of p-FOXO3A." (PMID 32587774, 2020). "Specific knockdown of CUL4A, CUL4B or DDB1 markedly decreases cancer cell growth." (PMID 32140073, 2020). "IP6 can promote the interaction between Cul4A and CSN2 to enhance Cul4A deneddylation, so IP6 or IP6K1 could be potential cancer treatment targets." (PMID 31394817, 2019). "Overexpression of CUL4A has been reported in several types of human cancers; however, its expression level in GC has not been characterized." (PMID 26840256, 2016). "Besides being involved in the ubiquitin-proteasome pathway, CUL4A is a transcriptional co-activator mediating EGFR and ZEB1 activation, which can promote cancer cell proliferation and EMT through epigenetic mechanisms." (PMID 26840256, 2016). "Elevated expression of CUL1 and CUL4A is observed in cancers, and UBE2M expression is elevated upon irradiation in cancer cells, suggesting the UBE2M-Cullin components are required for survival of the cancer cells." (PMID 25025768, 2014). "Importantly, these CUL4A/B paralogs are amplified or overexpressed in human carcinomas and provide negative prognostic markers for survival." (PMID 31690264, 2019). "Also, suggest an implication of CUL4A overexpression in cancer aggressiveness and progression rather than a major function as a transformation-initiating event." (PMID 24870930, 2014).
tumor (60 papers, 2007 to 2026). "In the present study, we evaluated the effects of CUL4A overexpression on autophagy to elucidate the possible mechanisms underlying iCCA tumor progression." (PMID 34257560, 2021). "We also provide evidence that high expression of CUL4A is associated with the larger tumor size, lymph node invasion and distant metastasis." (PMID 31860954, 2019). "The associations of Cul4A with the ANXA10 tumor suppressor and regulatory mechanisms were also studied." (PMID 31052599, 2019). "Our study found that expression of CUL4A was upregulated in tumor tissue of NPC, and is significantly associated with primary tumor size, modal status, distant metastasis, and clinical stage." (PMID 31860954, 2019). "The underlying biochemical mechanism through which CUL4A regulates tumor development and progression has been widely discussed." (PMID 28576144, 2017). "Using a two-class (human basal-like versus human non-basal) Fisher's exact test, we identified 29 DNA copy-number gains or losses commonly enriched in human basal-like tumor genomes (P-value<0.05), which included gains of Met and Cul4a and loss of Inpp4b." (PMID 27149990, 2016). "Tumors overexpressing either CUL4A or TFDP1 were associated with tumor proliferation and cell cycle progression markers." (PMID 19995430, 2009). "In addition to tumor size, surgical resection margin and tumor stage, CUL4A is an independent factor associated with DFS in iCCA patients." (PMID 28576144, 2017). "CUL4A, a member of the cullin family of proteins comprising the multifunctional ubiquitin-protein ligase E3 complex, is associated with the ubiquitination of tumor suppressor genes." (PMID 26684807, 2015). "Overexpression of CUL4A is associated with tumor proliferation, progression, and metastasis." (PMID 26684807, 2015). "Moreover, high level of CUL4A was positively associated with tumor pathological grade." (PMID 26593394, 2015). "We are the first group to validate CUL4A modulation of tumor-induced immunosuppression via the facilitation of PD-L1 degradation." (PMID 37027467, 2023). "Small-molecule PIK-93 modulates PD-L1 stability though CUL4A and benefits the tumor microenvironment for immunotherapy." (PMID 37027467, 2023). "LncRNA DLX6-AS1 acting as a miR-513c sponge was found to promote the tumor malignancy progression of HCC through modulating Cul4A/ANXA10." (PMID 36204642, 2022). "This study used NPC cells and tumor-bearing mouse models to explore the role and mechanism of CUL4A in NPC." (PMID 35333690, 2022). "The tumor volume in the Ov-CUL4A group increased sharply and was significantly larger than that in the Ov-NC group on the day of stripping." (PMID 35333690, 2022). "The tumor weight in the Ov-CUL4A group was also greatly larger than that in the Ov-NC group, and PRMT5 knockdown greatly inhibited the growth of tumor weight." (PMID 35333690, 2022). "Further tumor grade analyses of multiple clinicopathological features of TCGA-OV samples in the UALCAN database showed that CUL4A and DDB1 expression increased in tumors compared to paracancerous tissue in a non-grade-dependent manner." (PMID 36481655, 2022). "Their levels in the tumor of the Ov-CUL4A group were elevated and partly reversed in the Ov-CUL4A + shRNA-PRMT5 group." (PMID 35333690, 2022). "Endogenous Tet1 proteins were able to precipitate Cul4A/B, VprBP and Uhrf1 in the tumor cell line MCF7, which showed higher levels of Tet1s." (PMID 36056023, 2022). "The present study showed that CUL4A was overexpressed in NPC tissues compared to tumor-adjacent normal tissues." (PMID 31860954, 2019). "For example, Cul4A was reported to activate ZEB1 in tumor progression and tbx5 expression in zebrafish development by promoting H3K4 methylation." (PMID 31101894, 2019). "The results showed that CUL4A expression was significantly correlated with larger tumor size (P = .026), and lymph node involvement (P = .013), distant metastasis (P = .020), and clinical stage (P = .005)." (PMID 31860954, 2019).
tumor (continued). "An increased expression of Cul4A was observed in 59 (80.8%) tumor tissues compared to the paired normal tissues." (PMID 31052599, 2019). "High CUL4A expression was positively correlated with clinicopathological parameters, such as larger primary tumor size, higher incidence of nodal status, distant metastasis, and advanced clinical stage." (PMID 31860954, 2019). "Epigenetic modification, such as histone methylation, is another of the diverse mechanisms through which CUL4A affects tumor progression." (PMID 28576144, 2017). "Taken together, these results clearly suggest that overexpression of CUL4A can serve as an adverse prognostic factor mainly through promoting tumor progression with increased cell motility." (PMID 28576144, 2017). "A significantly increased expression of Cul4A mRNA was noted in NSCLC tumour compared to paired normal lung tissue samples." (PMID 26969027, 2016). "In the present study, we show that CUL4A expression is correlated with tumor-node-metastasis (TNM) clinical stages of GC." (PMID 26840256, 2016). "For example, knockdown of the tumor genes such Cul4A, Cul4B, and Wdr23 increased double-stranded DNA breaks following changes in cell cycle." (PMID 26942699, 2016). "Compared to a negative control lentivirus, lentivirus-mediated knockdown of CUL4A significantly inhibited growth of HGC-27 tumor xenografts." (PMID 26840256, 2016). "Statistical analysis disclosed an inverse correlation between CUL4A expression and tumor differentiation grade, and patient survival, but a positive correlation with hepatocyte proliferation as well as lymphatic and venous invasion." (PMID 26593394, 2015). "Further functional assay showed that CUL4A overexpression significantly promoted growth of H22 tumor homografts in BALB/c mice." (PMID 26593394, 2015). "Together, these studies suggest that increased Cul4A expression promotes tumour cell growth and is critical to tumour cell survival." (PMID 26218750, 2015). "CUL4A expression in poorly-differentiated tumors was significantly higher than that in well-differentiated or moderately-differentiated tumor tissues (P = 0.0006)." (PMID 26593394, 2015). "Subsequent active research spanning over a decade has highlighted the role of CUL4A complexes in regulating substrates involved in the cell cycle, signalling, tumour suppression, DNA damage response and chromatin remodelling." (PMID 24522884, 2014). "Conversely, a number of putative or known tumor suppressors were down-regulated in CUL4A-overexpressing cells and/or overexpressed in CUL4A knocked down cells." (PMID 24870930, 2014). "Recent evidence also highlights CUL4A's essential role in ubiquitination of several well-defined tumour suppressor genes." (PMID 24522884, 2014). "The CUL4A protein appeared to be expressed in both cytoplasmic and nuclear components of tumor cells with stronger signal observed in cytoplasm." (PMID 25413624, 2014). "We have recently shown that mechanistically Wnt10b-driven (Wnt10bTG) tumours degrade the tumour suppressor p27Kip1 in a SKP2-independent manner mediated by CUL4A E3-ligase activity leading to increased proliferation." (PMID 23307470, 2013). "These associations support that the overexpression of CUL4A and TFDP1, even though it is correlated with Amp13q34, is not exclusive of basal-like tumors, but still relates to higher tumor aggressiveness." (PMID 19995430, 2009). "We showed that CUL4B is important for tumor cell growth, similar to its paralog, CUL4A." (PMID 37686215, 2023). "Moreover, there are more than one E3 ubiquitin ligase for LATS1, further investigations are needed to characterize other CUL4A adaptors or additional E3 ligases in the regulation of tumor progression by S100A16." (PMID 37151881, 2023). "Thus, the majority of CUL4B is localized in the nucleus, whereas CUL4A is mainly localized in the cytoplasm of cells, including mesothelioma tumor cells." (PMID 37686215, 2023).